CD40 (CD40 molecule)
Diseases named in the same sentence as CD40 in open-access papers (continued):
Sharing a sentence is not in itself a finding about the gene and the disease.
Salmonella Infections (3 papers, 2015 to 2024). Infections with bacteria of the genus SALMONELLA. "Overall, our data using mice with a single or double deficiency in MyD88 and CD40 revealed that synergistic effects of CD40 and MyD88 do not influence host survival to Salmonella infection, CFUs in infected tissues or serum levels of IFN-γ or IL-10." (PMID 26441965, 2015). "Overall, our data revealed that synergistic effects of CD40 and MyD88 do not influence host survival to Salmonella infection or serum levels of IFN-γ or IL-10." (PMID 26441965, 2015).
sarcoma (3 papers, 2022 to 2025). A usually aggressive malignant neoplasm of the soft tissue or bone. "In addition, previous work has shown CD40 signaling to trigger an M1-like phenotype on macrophages in a model of chemically induced sarcomas." (PMID 35903540, 2022). "In comparison, the proportions of patients who had high CD40 expression and low-moderate CD40L expression were 20% (4/20) in lung, 17% (4/24) in sarcoma, 16% (4/25) in stomach, 8% (2/24) in uterine, 8% (11/140) in colorectal, and 4% (2/49) in breast." (PMID 41182434, 2025).
splenic marginal zone lymphoma (3 papers, 2021 to 2023). Splenic marginal zone lymphoma is a rare, indolent B-cell non-Hodgkin lymphoma characterized by abnormal clonal proliferation of mature B-lymphocytes with involvement in the spleen, bone marrow and, frequently, the blood. "However, as in the L.CD40 tumor model and in spleen marginal zone lymphomas, the PD1/PD-L1 axis is most likely playing a role in the immune escape of aggressive tumor B-cells with MYD88 activation." (PMID 34017329, 2021).
ZIKV infection (3 papers, 2017 to 2022). "To determine the ability of ZIKV infection to program DCs, we measured cell surface expression of co-stimulatory (CD80, CD86, and CD40) and MHC class II molecules at 48hpi with all four ZIKV strains." (PMID 28152048, 2017). "The correlations unique to acute ZIKV infection (e.g., positive correlations in the proportion of CD38+ pDCs and CD38+ Th1 CD4+ T cells, or between CD40+ cDCs and Ki-67+ DN B cells) may reflect interactions that are essential to mount a productive antiviral immune response." (PMID 35584677, 2022).
acute kidney injury (2 papers, 2019 to 2026). Sudden and sustained deterioration of the kidney function characterized by decreased glomerular filtration rate, increased serum creatinine or oliguria. "Specific EV antigens were associated with key clinical outcomes: CD20 and CD2 levels differed between patients with or without infections (bacterial, viral, and fungal) developed during hospitalization; CD40 and CD146 were elevated in patients who developed acute kidney injury." (PMID 41683683, 2026).
acute lymphoblastic leukaemia (2 papers, 2009 to 2017). "In lymphoid malignancies, CD40 is present on B-cell precursor acute lymphoblastic leukaemia (ALL), non-Hodgkin's lymphoma (NHL), Hodgkin's lymphoma (HL) and multiple myeloma (MM)." (PMID 19066610, 2009). "Following CpG ODNs stimulation, the expression levels of CD40, CD54, CD80, CD86, and MHC class I and II are all significantly increased in B-CLL cells, whereas only the expression of CD40 is significantly upregulated in acute lymphocyte leukemia cells." (PMID 28241765, 2017).
allergic rhinitis (2 papers, 2020 to 2021). Inflammation of the nasal mucous membranes caused by an IgE-mediated response to external allergens. "Targeting the CD40/CD40 ligand (CD154) interaction by CD40 siRNA given to bone-marrow-derived DCs attenuated allergic rhinitis and induced the conversion of CD4+ T cells into regulatory T cells." (PMID 31991941, 2020).
bile duct cancer (2 papers, 2021 to 2025). "We also examined CD40 expression in human tissues, showing that more than 50% of tumor samples of different patients suffering from pancreatic, colorectal or bile duct cancer, have a positive CPS for CD40 of more than 10%." (PMID 33180184, 2021).
bladder tumor (2 papers, 2021). "In bladder tumors, CD40 is mainly expressed by DCs and MHCII+ TAMs." (PMID 34572939, 2021).
brain tumors (2 papers, 2013 to 2022). "CD40-agonistic immunotherapies under investigation for the treatment of brain tumors include Sotigalimab and 2141-V11, with expected completion by the end of 2022 and 2025, respectively." (PMID 35456932, 2022).
cardiac hypertrophy (2 papers, 2016 to 2025). "The adipocyte-specific CD40 KO did not improve cardiac hypertrophy and systolic blood pressure in hypertensive animals." (PMID 39899926, 2025).
cerebral infarct (2 papers, 2010 to 2022). "We utilized CD40 as a molecular marker to visualize the RB-induced cerebral infarctions." (PMID 21203502, 2010).
Cerebral ischemia (2 papers, 2014 to 2021). Restriction of arterial blood supply to the brain associated with insufficient oxygenation to support the metabolic requirements of the tissue. "Apart from 2 articles focusing on respectively B-cell activation by targeting CD40 with nanoparticles and cerebral ischemia by targeting CD40 with an anti-CD40 antibody conjugated to Cy5.5, no pre-clinical advances in the field of NIRF imaging can be addressed using CD40 as a target." (PMID 33535618, 2021).
cervical disease (2 papers, 2021 to 2023). "Another study evaluated the expression of CD40 in tissue samples (normal cervical tissue, cervicitis, low- and high-grade lesions, and cancer)." (PMID 37970926, 2023). "What stood out in the tables was the patients afflicted with the cervical disease showed positive correlation significantly, such as famous immune checkpoint genes (CTLA4, TIGIT, HAVCR2, LAG3, etc.)and costimulatory genes like ICOS, CD80, CD40, and so forth." (PMID 33694292, 2021).
colorectal tumor (2 papers, 2020 to 2021). "The potential of this combination regimen is not just limited to PDAC, since IL‐15 and CD40 agonist therapy has been tested by others in mice bearing established CT26 and MC38 colorectal tumors." (PMID 32821382, 2020).
common variable immunodeficiency (2 papers, 2014 to 2017). "Behcet disease, X-linked CD40/CD40L mutations and secondary agammaglobulinemia were excluded according to ESID criteria for common variable immunodeficiency (CVID)." (PMID 29233117, 2017).
demyelinating disease (2 papers, 2015 to 2021). A broad group of disorders that affect the myelin sheaths that cover the neurons. "Further work is needed to understand the consequences of decreased CD40 expression on B lymphocyte and dendritic cells in antiviral/immunoregulatory functions in demyelinating disease, and what drives reduced expression of CD40 in B lymphocytes in established MS." (PMID 26068105, 2015). "CD40 on microglia plays an essential role in both direct neuroprotection as well as modulation of immune responses that may lead to improved neurologic outcomes in CNS infections and related demyelinating disorders." (PMID 34898656, 2021).
dengue (2 papers, 2019 to 2021). "Besides decreased percentages of CD24hiCD38hi transitional B cells/Bregs and CD27− naïve B cells in severe dengue infection, we also demonstrate here the inability of B cells isolated from dengue patients to produce IL-10 and TNF-α upon TLR/CD40 stimulation." (PMID 31736948, 2019).
endometrial cancer (2 papers, 2016 to 2017). Primary or metastatic malignant neoplasm involving the endometrium (mucous membrane that lines the endometrial cavity). "When the data were combined into two categories at the 25th fraction for the gene CD40 for endometrial cancer patients, this only resulted in six samples for the grade 1 category and two samples for the grade 3 and grade 4 categories." (PMID 28443095, 2017). "In endometrial cancer patients, we observed by simple visual screening that the expression of CD40 and OAS2 was particularly variable in patient E9 at the different time points studied although the number of patients studied here didn’t allow us to conclude in terms of statistical significance." (PMID 28443095, 2017).
fibromyalgia (2 papers, 2022 to 2026). A chronic disorder of unknown etiology characterized by pain, stiffness, and tenderness in the muscles of neck, shoulders, back, hips, arms, and legs. "The top five proteins that distinguished fibromyalgia patients from plasma controls were in serum STAMBP, SIRT2, CD40, AXIN1 and IL-7 and in CSF (CCL19, CCL23, IL-18, CX3CL1, FGF19, CXCL10, CCL11)." (PMID 36327322, 2022).
giant cell arteritis (2 papers, 2022 to 2024). "In contrast, a potential influence of CD40 rs1883832 and BLK rs2736340 polymorphisms was previously reported on the development of ischemic manifestations in patients with giant cell arteritis." (PMID 36233442, 2022).
gonorrhea (2 papers, 2024 to 2025). A common sexually transmitted bacterial infection caused by Neisseria gonorrhoeae. "Both Alum and MF59 significantly enhanced CD40 expression when used as a combination adjuvant with Polymyxin B MPs in comparison to the Polymyxin-adjuvanted gonorrhea vaccine." (PMID 41441698, 2025). "CD40 expression was significantly higher in the gonorrhea vaccine group when adjuvanted with Polymyxin B MPs than with MF59 and not significantly different from Alum." (PMID 41441698, 2025). "To further assess the adjuvant effect of Polymyxin B MPs with bacterial vaccine candidates, we analyzed the expression of MHC I, MHC II, CD40, and CD80 on dendritic cells after exposure to microparticulate gonorrhea vaccine formulations." (PMID 41441698, 2025).
graft versus host disease (2 papers, 2018 to 2022). An immune system disorder that occurs after allogeneic hematopoietic stem cell transplant and is a reaction of donor immune cells against host tissues. "Similarly, in a chronic graft versus host disease (GVHD) model of SLE generated by transfer of splenocytes from 6.C-H2bm12/KhEg mice into BL6 or BL6 miR-21−/−, lack of miR-21 showed a drastic reduction in autoantibody titers, CD40:CD40L and CD28:CD80/86 stimulation signals." (PMID 30322050, 2018).
Granuloma (2 papers, 2010 to 2023). A compact, organized collection of mature mononuclear phagocytes, which may be but is not necessarily accompanied by accessory features such as necrosis. "The amount of NADPH increased upon stimulation with IFN-γ, anti-CD40 antibody, and Con A, but decreased with the addition of 6AN and FBPi in this in vitro granuloma model." (PMID 38038136, 2023). "By flow cytometric analysis, we found that CD11c+ cells in chronic granulomas had lower expression of MHCII and co-stimulatory molecules CD40, CD80 and CD86, and higher expression of inhibitory molecules PD-L1 and PD-L2 compared to CD11c+ cells from acute granulomas." (PMID 20625513, 2010).
Graves ophthalmopathy (2 papers, 2015 to 2017). An autoimmune disorder of the EYE, occurring in patients with Graves disease. "In vitro studies demonstrated that the activation of CD40 on orbital fibroblasts leads to increased glycosaminoglycan productions, suggesting an important role in the pathogenesis of Graves’ ophthalmopathy." (PMID 29254239, 2017). "The present study was designed to investigate the expression of mRNA of the immune regulatory molecules FOXP3, CTLA-4/CD28/CD80/CD86, and CD40/CD40L in the orbital tissues from patients who underwent orbital decompression due to Graves' orbitopathy to assess their role in the inflammatory process." (PMID 25653477, 2015).
hepatitis B (2 papers, 2012 to 2020). "Furthermore, the positive correlation was observed between the serum levels of soluble CD40 and the deficient response to hepatitis B vaccination." (PMID 23326280, 2012). "In addition, the BK-F series proved to efficiently remove the soluble CD40, a dimeric or oligomeric protein ranging from 5 KD to 15 KD, which acts as a natural antagonist of the CD40/CD40L; the removal of this antagonist molecule is able to promote patients’ response to hepatitis B immunization." (PMID 32408613, 2020).
hypophysitis (2 papers, 2016 to 2018). Inflammation of the pituitary gland. "Of note, three patients in the lowest dose level developed grade (G) 2 hypophysitis were previously treated with CPI (2 with Ipilimumab, 1 with anti-CD40 inhibitor)." (PMID 30338242, 2018). "The appearance of hypophysitis in 3 checkpoint-treated patients (2 with ipilimumab, 1 with CD-40 monoclonal antibody) who did not have preexisting hypopituitarism suggests that indoximod helped to break tolerance after they were primed with the prior therapy months before going on this study." (PMID 27008709, 2016).
IgA nephropathy (2 papers, 2019 to 2023). "The median serum levels of anti-CD40 antibodies were significantly higher in the FSGS and MCD groups than in the controls and other glomerulopathies (membranous nephropathy, IgA nephropathy, and MPGN)." (PMID 37409273, 2023).
kidney cancer (2 papers, 2010 to 2021). Primary or metastatic malignant neoplasm involving the kidney. "Other forms of therapy have been demonstrated to impact on orthotopic kidney cancer in mice, including the use of IL-2 in combination with anti-CD40 or IL-12 in the Renca system." (PMID 20426873, 2010). "A combination of three antibodies targeting DR5, CD40 and CD137, termed Tri-mAb, was able to induce complete regression of syngeneic breast and kidney cancers located subcutaneously." (PMID 20426873, 2010). "The cancer-type-specific predictive performance of CD40 in ICB response suggests additional features of the TME may be involved in bladder and kidney cancers." (PMID 34758832, 2021).
kidney damage (2 papers, 2015 to 2019). "Analysis of the distribution of CD40 and CCL5 mRNA expression by ISH revealed a focal distribution pattern in the kidney cortex in DOX nephropathy similar to that observed in healthy mice receiving the activating CD40 mAb." (PMID 26623936, 2015). "In summary, antisense inhibition of CD40 in established DOX nephropathy mitigated functional, transcriptional, and pathological assessments of disease severity and sharply attenuated CD40-dependent inflammatory responses in the kidney." (PMID 26623936, 2015). "We evaluated the renal suborgan expression of CD40 mRNA in mice with early stage doxorubicin-induced (DOX) nephropathy and healthy controls." (PMID 26623936, 2015). "In the present study, we hypothesized that blocking the co-stimulatory CD40-CD40L signaling by siRNA-CD40 (small inhibitory RNA anti-CD40) administration would reduce the inflammatory response and kidney damage in the obstructive nephropathy." (PMID 30978213, 2019). "CD40 ASO treatment mitigated functional, transcriptional, and pathological endpoints of doxorubicin-induced nephropathy." (PMID 26623936, 2015). "CD40 ASO treatment mitigated functional, transcriptional, and histologic assessments of DOX nephropathy." (PMID 26623936, 2015). "Interestingly, the particular disease state (e.g., DOX nephropathy or UUO) did not make for qualitative differences in the distribution of renal CD40 expression, nor did the administration of the activating CD40 mAb." (PMID 26623936, 2015).
large artery stroke (2 papers, 2022 to 2024). Stroke caused by the blockage of blood flow in one of the large arteries feeding the brain. "Higher genetically predicted levels of both MMP12 (OR[95%CI] = 0.793[0.73, 0.861]; P = 3.53 × 10−8) and CD40 (OR[95% CI] = 0.795[0.723, 0.874]; P = 2.09 × 10−6) were associated with lower risk of large artery stroke." (PMID 36253349, 2022).
laryngeal carcinoma (2 papers, 2017 to 2024). Carcinoma that arises from the laryngeal epithelium. "Based on our research, the CD40 (rs1883832) polymorphism we detected in patients can be used as a criterion for determining the susceptibility of individuals to laryngeal cancer." (PMID 39625893, 2024). "This study, conducted in Turkish society, found a difference between the laryngeal cancer patient group and the control group regarding CD40 (rs1883832) genotype and allele distributions." (PMID 39625893, 2024). "According to the current findings, it is suggested that the CD40 (rs1883832) gene variation found in patients may indicate an individual’s susceptibility to developing laryngeal cancer." (PMID 39625893, 2024). "Furthermore, NSCLC tumors, tightly linked to laryngeal cancer by cellular origin and histology, have been reported to express another activator of the alternative NF-κB pathway, CD40 and its ligand, CD154, providing another possible molecular mechanism for alternative NF-κB activation." (PMID 29371965, 2017). "We identified a significant difference in the genotype distribution of CD40 (rs1883832) between laryngeal cancer patients and healthy individuals (p = 0.05)." (PMID 39625893, 2024). "After conducting a thorough literature review, we could not find any studies that have specifically addressed the CD40 (rs1883832) polymorphism in patients with laryngeal cancer." (PMID 39625893, 2024). "Our study investigates the impact of alterations in CD40 (rs1883832) and CD40L (rs1126535) genes and the levels of their proteins on the development of laryngeal cancer." (PMID 39625893, 2024). "Although no prior studies have specifically examined CD40 and CD40L levels in laryngeal cancer, research on other cancer types consistently reports an increase in CD40L levels alongside elevated CD40 levels in malignancies." (PMID 39625893, 2024). "Our literature review did not locate a study evaluating whether CD40 (rs1883832) and CD40L (rs1126535) polymorphisms increase susceptibility to laryngeal cancer." (PMID 39625893, 2024).
latent infection (2 papers, 2015 to 2017). "Recent studies demonstrate that latent infection with γ-herpesvirus-68, the murine homologue of Epstein-Barr virus, upregulates CD40 expression, facilitating and exacerbating EAE." (PMID 28192476, 2017).
Lewis lung carcinoma (2 papers, 2015 to 2025). "Taken together, these results strongly suggest that Anti-CD40-induced inflammatory E-cadherin + DCs promote T cell responses and antitumour activity in murine Lewis lung carcinoma." (PMID 25651850, 2015). "This study investigated the effect of anti-CD40-mediated inflammatory E-cadherin + DCs in murine Lewis lung carcinoma (LLC)." (PMID 25651850, 2015).
lung disease (2 papers, 2020 to 2025). "Again, anti-CD40 antibody treatment reduced the pulmonary disease burden in WT but not in Keap1flox/flox VavCre mice." (PMID 41176316, 2025). "These include CD14, CD40, and CD80, which are surface receptors that trigger NF-κB activation, and IL-8, IL-6, and RANTES that are NF-κB-responsive cytokines with major roles in the pathogenesis of CF lung disease." (PMID 32528461, 2020).
lymphopenia (2 papers, 2010 to 2011). Reduction in the number of lymphocytes. "In view of our current findings it is likely that the in vivo use of CD40-agonists may ensure fast effector cell recoveries during lymphopenia restoration." (PMID 21423804, 2011). "Since lymphopenia is induced by irradiation in our model, activation of the cross-presenting APCs could by-pass the need for CD40 engagement by CD4+ T helpers." (PMID 20856822, 2010).
malignant mesothelioma (2 papers, 2014 to 2015). A malignant neoplasm of the pleura or peritoneum, arising from mesothelial cells. "Regarding the administration method, it was reported that the local administration of the TLR7 agonist imiquimod with anti-CD40 immunotherapy exhibited a strong antitumour effect in a murine model of malignant mesothelioma." (PMID 25887995, 2015). "We therefore tested the efficacy of the TLR7 agonist imiquimod (IMQ) combined with agonistic anti-CD40 in an incomplete debulking model of malignant mesothelioma." (PMID 25518732, 2014).
measles (2 papers, 2024 to 2025). A highly contagious viral infection caused by the measles virus. "The CD40 expression in measles + Polymyxin B MPs was significantly comparable to measles + Alum MPs and higher than measles + MF59 MPs." (PMID 41441698, 2025). "The co-adjuvant strategy with MF59 or Alum in the Polymyxin B-adjuvanted measles vaccine did not significantly increase CD40 expression in comparison to measles + Polymyxin B MPs." (PMID 41441698, 2025).